EPCAM (epithelial cell adhesion molecule)
Diseases named in the same sentence as EPCAM in open-access papers (continued):
Sharing a sentence is not in itself a finding about the gene and the disease.
Lynch syndrome (continued). "Previous studies have reported that the deletion of the EPCAM gene is associated with CTE and Lynch syndromes through different mechanisms." (PMID 38791091, 2024).
Lynch syndrome (continued). "The incidence of EPCAM deletion varies among populations and was shown to account for at least 1–3% of the explained Lynch syndrome families." (PMID 34118983, 2021). "Uninformative germline genetic testing presents a challenge to clinical management for patients suspected to have Lynch syndrome, a cancer predisposition syndrome caused by germline variants in the mismatch repair (MMR) genes or EPCAM." (PMID 34397043, 2021). "Mutations in the EpCAM gene were reported in patients having Lynch syndrome through deletions in the 3’UTR 29 or congenital tufting enteropathy that results in decreasing EpCAM protein level." (PMID 35070966, 2021). "The other causes of the higher incidence of Lynch syndrome in our series were that we included patients with EMAST phenotypes and target sequences of MMR‐associated genes, including a high frequency of EPCAM mutations." (PMID 31769227, 2020). "Molecular analysis of the mismatch repair genes and EPCAM gene is required for a definitive diagnosis of Lynch syndrome." (PMID 30238922, 2019). "Lynch syndrome is caused by genetic defects at the level of MMR components, particularly by germline mutations of one of the MMR genes (hMSH2, hMLH1, hPMS2, hMSH6, EPCAM), followed by the somatic inactivation of the second allele." (PMID 29652830, 2018). "EPCAM-CL can be used to screen for EPCAM deletion-induced Lynch syndrome-associated CRC, whereas EPCAM-PL can be used as an indicator of tumor aggressiveness and poor prognosis in CRC." (PMID 26528695, 2016).
Lynch syndrome (continued). "Larger numbers of Lynch syndrome families and screening of the two additional predisposition genes, PMS2 and EPCAM, are needed in order to decipher the full spectrum of mutations associated with Lynch syndrome predisposition in Cyprus." (PMID 25133505, 2014). "It has recently been shown that germline deletions of the last few exons of the EPCAM gene are involved in the etiology of Lynch syndrome." (PMID 23938213, 2013). "The incidence of EPCAM deletions appeared to vary between populations and was found to represent at least 1-3% of the explained Lynch syndrome families." (PMID 23938213, 2013). "According to recent studies there is another gene that has an impact on Lynch syndrome (in approximately 1-3% of LS patients within the Dutch and German populations) and this is the EPCAM gene." (PMID 23938213, 2013). "EPCAM deletions account for 1%–3% of cases of Lynch syndrome." (PMID 41214301, 2026).
Lynch syndrome (continued). "EPCAM deletions have been reported to account for 1–3% of Lynch syndrome cases." (PMID 34185173, 2021). "However, this study was limited by our inability to test other MMR gene germline mutations associated with Lynch syndrome, including MSH6, PMS2, and EPCAM germline mutations." (PMID 27907203, 2016). "In addition, deletions in the EPCAM gene have also been reported in approximately 1%–3% of Lynch syndrome patients within Dutch and German populations." (PMID 26053027, 2015). "In addition, this study was limited by our inability to test for other MMR gene germline mutations that are also associated with Lynch syndrome, such as MSH6, PMS2 and EPCAM germline mutations." (PMID 26053027, 2015). "If Lynch syndrome is suspected in a cancer patient, DNA testing can be used to determine whether the patient has a MMR or EPCAM gene mutation." (PMID 24056992, 2013). "Expression of hMLH1, hMSH2, and EPCAM is suppressed by promoter hypermethylation, which inhibits direct or indirect DNA mismatch repair and contributes to development of endometrial cancer type 1 and development of endometrial cancer in Lynch syndrome." (PMID 22548175, 2012).
Lynch syndrome (continued). "Therefore, deletion analysis of EPCAM is appropriate for the diagnosis of Lynch syndrome." (PMID 34118983, 2021). "The frequent occurrence of somatic deletions affecting the EPCAM gene as a second hit in tumors from EPCAM deletion carriers suggests that the localization of somatic events inactivating mismatch repair genes in Lynch syndrome is not random, but related to the underlying germline mutation." (PMID 23938213, 2013). "Genetic mutations in EpCAM have been described to be responsible for congenital tufting enteropathy (CTE), intractable diarrhea in infants, and Lynch syndrome (also known as hereditary non-polyposis colorectal cancer or HNPCC)." (PMID 39996844, 2025).